APC (APC regulator of Wnt signaling pathway)
Diseases named in the same sentence as APC in open-access papers (continued):
Sharing a sentence is not in itself a finding about the gene and the disease.
Familial adenomatous polyposis (continued). "SBA risk factors were identified: two (2.1%) patients had personal history of celiac disease, five (5.3%) had inflammatory bowel disease (four Crohn’s disease and one ulcerative colitis) and one (1.1%) had familial adenomatous polyposis syndrome with a known pathogenic mutation on the APC gene." (PMID 34944998, 2021). "Among 53 patients with normal WES data, two harbored germline APC-truncating variants, and endoscopy revealed numerous polyps concurrent with germline variants in these patients; the two patients were diagnosed with familial adenomatous polyposis." (PMID 33753878, 2021). "APC is also the gene mutated in familial adenomatous polyposis (FAP), an inherited form of CRC." (PMID 33193386, 2020). "Twenty-six familial adenomatous polyposis (FAP) patients with 15 putative de novo APC mutations that may arise during the meiosis have also been reported." (PMID 33260537, 2020). "All familial adenomatous polyposis patients and more than 85% of the sporadic cases of colon cancer carry genetic mutations in the APC gene, resulting in the complete or partial inactivation of the APC protein[62 ▶,63 ▶]." (PMID 32429632, 2020). "Notably, germline APC mutations are one of the main cause of familial adenomatous polyposis, while somatic APC mutations are evident in eight out of 10 sporadic CRCs." (PMID 31390840, 2019). "Interestingly, colonic organoids were obtained from patients with familial adenomatous polyposis harboring gene mutations in the WNT-signaling-pathway regulator gene encoding APC, representing a unique platform for the evaluation of drug sensitivity." (PMID 29652830, 2018). "Moreover, patients with familial adenomatous polyposis (FAP) are reported to show loss-of-function mutations in the APC gene." (PMID 29966001, 2018). "Individuals who develop familial adenomatous polyposis have a mutation in the APC (adenomatous polyposis of the colon) tumor suppressor gene, whereas those who develop hereditary nonpolyposis colorectal cancer have mutations in genes involved in DNA repair and mismatch repair (MMR) genes." (PMID 29972397, 2018). "CRC can be classified by etiology as hereditary (e.g. familial adenomatous polyposis due to an initiating mutation in the Adenomatous Polyposis Coli (APC) gene), inflammatory (associated with Crohn’s disease and ulcerative colitis), or sporadic (in more than 80% of cases)." (PMID 29687353, 2018). "Furthermore, APC is mutated in familial adenomatous polyposis (FAP), which facilitates the evolution of CRC." (PMID 28164117, 2017). "Overall, our study demonstrates that targeting of PrxII may exert specific and broad therapeutic potentials for treating familial adenomatous polyposis as well as APC-mutation-positive CRCs." (PMID 28659575, 2017). "Germline mutations of the APC gene are responsible for familial adenomatous polyposis (FAP)." (PMID 28576136, 2017). "The majority of human sporadic CRC cases (ca. 85%) follow the chromosomal instability pathway, where mutations in one allele of the tumor suppressor gene APC (adenomatous polyposis coli) are typically followed by mutations in, or by loss of heterozygosity (LOH) of the remaining allele." (PMID 28426718, 2017). "Indeed, we have used TALENs to construct a swine models of the cancer predisposition disease, familial adenomatous polyposis by engineering a premature termination codon in APC." (PMID 27242889, 2016). "Patients with familial polyposis inherit the defective APC allele at an early age, which causes the formation of numerous adenomatous polyps in the colon, which results in the clonal growth of epithelial cells in which the second APC allele is made inactive." (PMID 25932044, 2015).
Familial adenomatous polyposis (continued). "In addition, bi-allelic inactivation of APC is rarely found in sporadic AC tumors, though patients with familial adenomatous polyposis APC mutation are common." (PMID 24755523, 2014). "Notably in humans, mutations in the APC gene represent an initiating factor in the process of colon carcinogenesis and can be detected in the vast majority of familial adenomatous polyposis (FAP) patients, and in 60–80% of sporadic colorectal tumors." (PMID 22848656, 2012). "Germline mutations in the adenomatous polyposis coli (APC) gene are responsible for familial adenomatous polyposis (FAP), an autosomal dominant hereditary predisposition to the development of multiple colorectal adenomas and of a broad spectrum of extra-intestinal tumors." (PMID 19578404, 2009). "Genetic alterations also appear to modulate stem cell dynamics because certain germline APC mutations are associated with significantly more diverse tags in normal-appearing familial adenomatous polyposis colon crypts, consistent with increased niche stem cell survival." (PMID 15975143, 2005). "Adenomatous polyposis coli acts as a gatekeeper for cellular proliferation in the colon and, although mutations in APC may initiate adenoma formation, additional somatic changes are required for progression to carcinoma." (PMID 15083190, 2004). "Germline genetic test detected a heterozygous, pathogenic germline mutation in the APC (C1270*), which indicated familial adenomatous polyposis (FAP)." (PMID 40491286, 2026). "Familial adenomatous polyposis (FAP) is a hereditary disorder caused by pathogenic germline mutations in the adenomatous polyposis coli (APC) gene, with an estimated prevalence ranging from one in 8500 to 20,000 individuals." (PMID 41000433, 2026). "Familial adenomatous polyposis (FAP) is a hereditary condition caused by germline mutations in the APC gene, resulting in the development of hundreds to thousands of adenomatous polyps in the colon and rectum, often during adolescence or early adulthood." (PMID 39936971, 2025). "People with polyposis could have a genetic basis with germline mutations in polyposis-related genes, such as the APC gene, resulting in familial adenomatous polyposis (FAP), MUTYH-associated polyposis (MAP), or, rarely, in other genes such as AXIN2, GREM1, NTHL1, POLE, POLD1, or MSH3." (PMID 40095498, 2025). "Pathogenic variants within the 5′ alternatively spliced region of APC exon 9 are associated with attenuated familial adenomatous polyposis (FAP), which generally effects a substantial polyp burden but is considered reduced relative to classic FAP." (PMID 41300834, 2025). "Familial adenomatous polyposis (FAP) is a dominantly inherited condition caused by pathogenic variants in the APC tumour suppressor gene which inevitably progresses to cancer if left untreated." (PMID 40911204, 2025). "Familial adenomatous polyposis (FAP) is an inherited CRC syndrome resulting from germline mutations in the adenomatous polyposis coli (APC) gene that is a negative regulator of the Wnt/β-catenin signaling pathway." (PMID 40136707, 2025). "Familial adenomatous polyposis (FAP) is an autosomal dominant inherited disorder caused by germline mutations in the APC gene located on chromosome 5q21." (PMID 41551144, 2025). "Familial adenomatous polyposis (FAP) is caused by a germline APC variant, which results in a nearly 100% lifetime risk of developing colon rectal cancer, in contrast to other tumor types which are relatively rare." (PMID 40940982, 2025). "Evidence that APC mutation drives tumor initiation and growth comes from familial adenomatous polyposis (FAP) patients who carry an APC germline mutation." (PMID 41514557, 2025). "For example, in a recent study, individuals with familial adenomatous polyposis (FAP) who had mutations in the APC gene were chosen as participants." (PMID 40282754, 2025).
Familial adenomatous polyposis (continued). "Desmoid-type fibromatosis (DF) typically occurs sporadically, but about 7.5–16% of cases are associated with familial adenomatous polyposis (FAP) and linked to mutations in the APC gene on chromosome 5q22." (PMID 41181483, 2025). "Familial adenomatous polyposis (FAP) is caused by pathogenic variants in the APC gene and is typically associated with colorectal polyps and an increased risk of colorectal and other cancers." (PMID 41467151, 2025). "Multistep carcinogenesis has been discovered through the study of familial adenomatous polyposis (FAP), an inherited disease with a germline APC variant." (PMID 41488735, 2025). "Familial adenomatous polyposis (FAP) results from germline APC mutations, predisposing individuals to thousands of colonic polyps." (PMID 41361128, 2025). "These intra-abdominal tumours are often associated with adenomatous polyposis coli (APC) gene mutation and familial adenomatous polyposis (FAP)." (PMID 39742373, 2024). "Similarly, germline mutations in APC lead to Familial Adenomatous Polyposis (FAP), a condition that may develop into a malignancy mostly in the colon." (PMID 38247798, 2024). "A hereditary cancer syndrome known as Familial Adenomatous Polyposis (FAP) results from a germline APC mutation." (PMID 38247798, 2024). "Cases with biallelic APC gene inactivation include occasional cases with confirmed germline APC gene mutation, suggesting that at least a subset may be associated with underlying familial adenomatous polyposis." (PMID 39597961, 2024). "Familial adenomatous polyposis (FAP) is an autosomal dominant genetic disorder that is caused by a germline mutation in the adenomatous polyposis coli (APC) gene." (PMID 39227904, 2024). "Conversely, hereditary cases, often associated with familial adenomatous polyposis (FAP) or Gardner syndrome, are linked to germline APC gene mutations." (PMID 39835056, 2024). "Familial adenomatous polyposis (FAP), caused by germline variants in the APC gene, is an autosomal dominant inherited syndrome." (PMID 39632802, 2024). "Mutations in the APC gene are not only responsible for familial adenomatous polyposis (FAP) but also play a rate-limiting role in the majority of sporadic CRC23–26." (PMID 39730571, 2024). "Germline mutations in APC are also responsible for familial adenomatous polyposis (FAP), a hereditary condition characterized by the development of hundreds to thousands of colorectal adenomas and an almost inevitable progression to CRC if left untreated." (PMID 39684219, 2024). "Traditionally, desmoid tumors are associated with familial adenomatous polyposis (FAP), primarily in its abdominal form resulting from a mutation in the APC gene." (PMID 38308981, 2024). "This abnormal activation can be attributed to either a germline mutation that leads to the loss of function of the tumor suppressor gene APC in the context of familial adenomatous polyposis (FAP), or somatic mutations occurring in the β-catenin gene (CTNNB1)." (PMID 39410565, 2024). "First, as the typical familiar EOCRC, familial adenomatous polyposis (FAP) is characterized by numerous colorectal adenomas, and the individuals with APC germline pathogenic mutations usually developed CRC before 40 years old." (PMID 36869385, 2023). ",65 iPSCs derived from patients with familial adenomatous polyposis (FAP) and carrying mutations in APC have been used for modeling colorectal cancer and evaluating drugs that reverse FAP." (PMID 37146581, 2023). "APC mutations are responsible for familial adenomatous polyposis (FAP), an autosomal dominant precancerous disease that typically leads to malignancy." (PMID 37835512, 2023). "Familial adenomatous polyposis (FAP) is defined by the presence of GPVs in the APC gene which predisposes an individual to colorectal and upper GI polyposis." (PMID 37258796, 2023).
Familial adenomatous polyposis (continued). "Moreover, in the case of APC variant identification, it could be helpful to suggest, in the pathology report, the possible association with familial adenomatous polyposis." (PMID 38136408, 2023). "HCAs can arise in the setting of familial adenomatous polyposis (FAP) coli with a germline mutation the APC gene." (PMID 37835484, 2023). "Multiple APC splice site mutations have been identified in FAP (familial adenomatous polyposis) patients." (PMID 37009804, 2023). "Familial adenomatous polyposis (FAP) is a hereditary cancer syndrome that occurs as a result of germline mutations in the APC gene." (PMID 36828923, 2023). "Familial adenomatous polyposis (FAP) is an autosomal dominant disorder with a high cancer rate, and mutations in the adenomatous polyposis coli (APC) gene are one of its pathogenic mechanisms." (PMID 35312122, 2022). "Germ-line mutations in the APC gene result in familial adenomatous polyposis (FAP), which is characterized by numerous polyps in the intestines, but mutations in APC have been also found in up to ~80% of sporadic carcinomas and adenomas." (PMID 36056393, 2022). "Chromosome arm 5q deletion has been widely reported in familial adenomatous polyposis (FAP), which is due to mutations of the APC gene." (PMID 35741793, 2022). "Familial adenomatous polyposis (FAP) is an autosomal dominant disease caused by loss-of-function mutations of the APC tumour suppressor gene located on chromosome 5q21." (PMID 35255942, 2022). "Familial adenomatous polyposis (FAP) is a rare autosomal dominant disease characterized by germline mutations in the Adenomatous Polyposis Coli (APC) gene, resulting in the development of numerous colorectal adenomas." (PMID 35962368, 2022). "Germ-line mutations in the APC gene are associated with familial adenomatous polyposis (FAP) and hereditary predisposition to develop CRC." (PMID 35053565, 2022). "Familial adenomatous polyposis (FAP) is related to mutation of the APC gene that results in numerous colon polyps and colorectal adenocarcinoma." (PMID 35565398, 2022). "Familial adenomatous polyposis (FAP), characterized by the presence of dozens to hundreds of colorectal adenomas, is a hereditary disease caused by germline variants in APC, a key tumor suppressor gene in the regulation of the WNT signaling pathway." (PMID 36232851, 2022). "Apart from generating familial adenomatous polyposis (FAP), mutations in both alleles of the APC gene have a rate-limiting role in most sporadic CRC." (PMID 35883434, 2022). "Familial Adenomatous Polyposis (FAP) is a rare premalignant hereditary autosomal-dominant condition due to germline mutations in the Adenomatous Polyposis Coli (APC) gene." (PMID 34836243, 2021). "Germline mutations in the APC gene are the genetic cause of familial adenomatous polyposis (FAP), an autosomal dominant syndrome characterized by numerous adenomatous lesions in the colorectum, and early onset CRC." (PMID 34575971, 2021). "Colorectal familial adenomatous polyposis (FAP) adenomas exhibit a uniform pathogenetic basis caused by a germline mutation in the adenomatous polyposis gene (APC), but the molecular changes leading to their development are incompletely understood." (PMID 33579312, 2021). "YAP activation is a prevalent characteristic of tubular adenomas from patients with familial adenomatous polyposis (FAP), a cancer syndrome linked to APC mutation." (PMID 34831147, 2021). "Germline mutations in APC lead to familial adenomatous polyposis (FAP) and account for about 1–2% of CRC." (PMID 34017835, 2021). "To show that depletion of CtBP2 functionally affects stemness in human adenoma cells with a mutation in APC, we made use of colonic epithelial organoids derived from adenomas of patients with familial adenomatous polyposis (FAP)." (PMID 33972635, 2021).
Familial adenomatous polyposis (continued). "Thus, individuals with familial adenomatous polyposis (FAP) that are heterozygous for a germline mutation inactivating one allele of APC exhibit spontaneous loss of heterozygosity that leads to hundreds of tumours, mostly restricted to the intestinal epithelium." (PMID 33335067, 2021). "Previously, a few case reports have described adamantinomatous craniopharyngioma formation in patients with familial adenomatous polyposis (FAP), characterized by germline mutations in APC." (PMID 34549183, 2021). "A higher risk for women for having a thyroid cancer is known in families affected by familial adenomatous polyposis syndrome (FAP), which is due to mutations in the APC gene." (PMID 34884794, 2021). "In fact, germline mutations in APC result in familial adenomatous polyposis (FAP) in humans, which is characterized by intestinal polyposis that affects both the colon and small intestine." (PMID 33372038, 2021). "The association of APC mutations and a hereditary cancer syndrome of familial adenomatous polyposis (FAP) is well known." (PMID 33919924, 2021). "Twenty-nine primer pairs flanking exons 2–16 (i.e., coding exons 1–15) of APC and their exon–intron junctions were used for germline pathogenic variant screening in Southern Thai patients with familial adenomatous polyposis (FAP)." (PMID 33740971, 2021). "A germline mutation of the APC gene causes familial adenomatous polyposis (FAP), a genetic disorder characterized by hundreds of polyps in the large intestine that, if left untreated, progress toward malignant carcinomas." (PMID 33303756, 2020). "Later, mutations in APC, β-catenin, and Axin were associated with genetic diseases such as familial adenomatous polyposis (FAP) in patients." (PMID 33126517, 2020). "Although CIN represents the main molecular pathway involved in sporadic CRCs, it is also observed in familial adenomatous polyposis (FAP), due to a germline mutation of the APC gene, with a 100% risk of developing CRC within the patient’s life-span." (PMID 32545884, 2020). "Initially, germline mutations of APC were discovered to underlie familial adenomatous polyposis (FAP), an inherited precancerous condition that ultimately gives rise to CRC." (PMID 32824859, 2020). "Germline mutations in APC deregulate the WNT signaling pathway to cause familial adenomatous polyposis (FAP)." (PMID 33202710, 2020). "In the 1990s, APC was identified as the cause of familial adenomatous polyposis (FAP), which is a heritable disorder that causes numerous adenomas throughout the intestinal tract." (PMID 33105836, 2020). "APCMin/+ mice harbor a heterozygous germline mutation in the APC gene and is an animal model with spontaneous tumorigenesis for familial adenomatous polyposis (FAP)." (PMID 32038097, 2020). "Familial adenomatous polyposis (FAP) is mainly caused by mutations in the APC gene, and the incidence of HB in patients with FAP is greatly increased." (PMID 32758256, 2020). "Familial adenomatous polyposis (FAP) is an autosomal dominant condition caused by loss-of-function in the adenomatous polyposis coli (APC) gene." (PMID 31211760, 2019). "Familial Adenomatous Polyposis (FAP) is caused by mutations in the adenomatous polyposis coli (APC) gene." (PMID 31226964, 2019). "Familial adenomatous polyposis (FAP) is caused by a mutation in the tumor suppressor, APC, and has been linked to patients with pancreatic cancer." (PMID 31540078, 2019). "Those with familial adenomatous polyposis (FAP) have a germline APC mutation that predisposes towards the growth of adenoma polyps." (PMID 30884915, 2019). "Two papers brought about wide appreciation of quantitative difference in gene expression between two alleles of APC in familial adenomatous polyposis (FAP)." (PMID 31497535, 2019).